IL6 (interleukin 6)
Diseases named in the same sentence as IL6 in open-access papers (continued):
Sharing a sentence is not in itself a finding about the gene and the disease.
depression (continued). "Similarly, human studies have consistently found that circulating levels of at least 15 markers such as CRP, IL-2, IL-6, CCL3, TNF-α, and TNF-β (also known as Lymphotoxin-alpha) were increased in patients with depression." (PMID 41010394, 2025). "More recently, a survey on the immune profile of people at the first episode of major depression documented a significant activation of immune circuit Th1 compared to the control group, with an increase in inflammatory cytokines such as TNF and IL-6 and also several chemokines." (PMID 40141399, 2025). "Furthermore, the pro-inflammatory cytokine IL-6 partially mediated the relationship between SGHS and depression." (PMID 40256164, 2025). "However, the majority of existing epidemiological studies have primarily examined relationships between interleukin-1b (IL-1b), interleukin-2 (IL-2), interleukin-6 (IL-6), tumor necrosis factor-alpha (TNF-a), and other inflammatory factors and depression." (PMID 40530060, 2025). "Moreover, several pro-inflammatory cytokines that play an essential role in depression, such as TNF-α, IL-1β, and IL-6, are suppressed by ghrelin." (PMID 41375608, 2025). "Mental health practitioners could incorporate inflammatory marker panels (e.g., IL-6, TNF-α, CRP) into assessment protocols, particularly for patients with depression subtypes characterized by elevated inflammation." (PMID 40964429, 2025). "Although fatigue is an indistinguishable depressive symptom in patients with depression, high serum IL-6 levels have been observed in various types of depression." (PMID 41239360, 2025). "Elevated IL-6 levels may lead to HPA axis dysfunction, altered synaptic neurotransmission, and reduced neurotrophic factors, which may generate depression." (PMID 40313235, 2025). "Among the key cytokines, interleukin (IL)-1β can interfere with neurotransmitter systems and trigger more inflammatory substances, while IL-6 often increases in people with depression, affecting the normal function of the hypothalamic–pituitary–adrenal axis." (PMID 40426956, 2025). "Additionally, moderate PA reduces systemic inflammation by lowering levels of pro-inflammatory cytokines, such as IL-6 and TNF, which are often elevated in individuals with depression." (PMID 40420074, 2025). "Depression activates the IRS, which produces pro-inflammatory factors such as TNF-α and IL-6." (PMID 39980978, 2025). "Patients with depression typically exhibit elevated levels of inflammatory markers, such as C-reactive protein (CRP), tumor necrosis factor-α (TNF-α), and interleukin-6 (IL-6), which can impact the functioning of the central nervous system, causing mood disorders and cognitive decline." (PMID 40313907, 2025). "Furthermore, emerging evidence identifies the combined biomarkers of elevated serum IL-6 levels and reduced BDNF concentrations as reliable predictors of depression severity, laying the foundation for multidimensional biomarker assessment systems." (PMID 41200224, 2025). "Additionally, a study by Järventausta and colleagues found that IL-6 levels decreased towards the end of ECT treatment, which correlated with patient response scores, as measured by the Montgomery–Åsberg Depression Rating Scale (MADRS)." (PMID 40565369, 2025). "In particular, about depression, there is growing evidence of a link between ACE and depression as adults, which is mediated by inflammation, recorded through increased IL-6 and TNF-α, but not by PCR." (PMID 40141399, 2025). "Patients with both psoriatic arthritis (PsA) and depression had statistically significantly higher levels of IL-1 and IL-6 in their peripheral blood than PsA patients without depression." (PMID 40141110, 2025). "Shared inflammatory pathways, including elevated IL-6, TNF-α, and IL-17, may link psoriasis with psychiatric disorders such as depression and anxiety." (PMID 40428224, 2025).
depression (continued). "Considering the promoting role of IL-6 in depression among COPD patients, we hypothesize an intrinsic link between IL-6 and psychosomatic syndromes." (PMID 40708589, 2025). "Similar to the PANSS depression model, combining both groups showed that higher levels of plasma IL-6 were significantly related to more negative symptoms (B = 0.78; 95% CI, 0.14 to 1.41; p = .017)." (PMID 39911538, 2025). "Notably, while ART partially normalizes certain depression-related inflammatory cytokines in HIV-infected individuals, others, such as IL-6 and CRP, remain elevated." (PMID 40977685, 2025). "In depression, pro-inflammatory cytokines such as IL-1β, IL-6 and TNF-α play a distinct role, not merely facilitating immune responses but also participating in the regulation of neurochemical, neuroendocrine and neuroplasticity processes." (PMID 40612748, 2025). "Study has suggested that individuals with depression generally display higher levels of interleukin-1 (IL-1), IL-6, TNF-α, and CRP compared to non-depressed individuals." (PMID 40313907, 2025). "Exposure to trauma was measured from 5 to 11 years of age; C-reactive protein and interleukin-6 levels were measured at 9 years; and depression, anxiety disorders, negative symptoms and psychotic experiences were assessed at 24 years." (PMID 40814293, 2025). "Second, this study focused exclusively on IL-1β, IL-6, and TNF-α as inflammatory biomarkers associated with depression and did not examine the effectiveness of MBTs on other inflammatory markers." (PMID 41194929, 2025). "In addition to elevated levels of IL-6 and TNF-α in depression, these cytokines have been proven to correlate with symptoms of MDD." (PMID 41226404, 2025). "The difference between IL-6 and IL-10 levels in women with and without depression was not statistically significant." (PMID 40682534, 2025). "The results revealed that pSS patients with either depression or anxiety (regardless of HADS category) had higher concentration of IL-6 (P < 0.001, P = 0.002, respectively)." (PMID 40822847, 2025). "It is possible that short-term fluctuations in IL-6 are related to episodic symptoms of depression but that they do not persist and foster chronic inflammation." (PMID 39902492, 2025). "NHR is a superior index compared to traditional markers like CRP and IL-6, as it combines neutrophil-driven immune activation with HDL-C’s anti-inflammatory effects, providing a more comprehensive view of the adiposity-inflammation-depression axis." (PMID 41162914, 2025). "Three studies reported significant differences in inflammatory protein concentrations between MS participants with and without depression for IL-6 in serum, and IL-9,30 TNF-α and CRP in both serum and CSF." (PMID 39867847, 2025). "What is more, a positive correlation between serum IL-6 levels and Hamilton Depression Rating Scale (HAM-D) scores has also been documented, suggesting a link between IL-6 concentration and symptom severity in depression." (PMID 41226404, 2025). "Mechanistically, IL-6, the levels of which are elevated systemically in IBD, permeates the BBB or relays signals via vagal pathways to suppress hippocampal neurogenesis and induce depression-like behaviors in preclinical models." (PMID 40909294, 2025). "Individuals with depression exhibit distinct gut microbiota profiles, including reduced abundance of short-chain fatty acid (SCFA)-producing bacteria (e.g., Faecalibacterium and Roseburia) and elevated pro-inflammatory cytokines (e.g., IL-6, TNF-α), correlating with depression severity." (PMID 41573044, 2025). "Increased levels of interleukin-6 (IL-6), interleukin-1β (IL-1β), CCl2, C-reactive protein (CRP), and TNF-α in the blood and cerebrospinal fluid were also detected in the patients haunting by depression." (PMID 40862788, 2025). "IL-6 and IL-17A produced by M1-type macrophages cross the BBB and activate M1-type microglia in the brain, which in turn release pro-inflammatory factors to induce depression." (PMID 41301929, 2025).
depression (continued). "The serum levels of Hs-CRP and IL-6 after delivery in women with depression were significantly higher than in women without depression." (PMID 40682534, 2025). "Encouragingly, research has identified that TNF-α, IL-1, and IL-6 mediate CRF development, indicating that CRF may share some neurophysiological mechanisms with mental health disorders like depression." (PMID 39935799, 2025). "In rats with CSVD and depression, PY significantly increased body weight; alleviated depression-like behaviors; and decreased the levels of inflammatory cytokines such as TNF-α, IL-1β, and IL-6 in both serum and hippocampus." (PMID 40584618, 2025). "Study had proved that Ziyan Green Tea administration could stimulate the levels of 5-HT, BDNF, and DA in the brain, and reduce the inflammatory factors, IL-6 and TNF-α, to prevent depression induced by CUMS." (PMID 39861389, 2025). "This process disrupts the activation of the IL-6/STAT3 signaling pathway, alleviating neuroinflammation by suppressing proinflammatory mediators, while enhancing synaptic plasticity ultimately ameliorates depression-like behaviors." (PMID 40949123, 2025). "This was confirmed with multivariate, stepwise, linear regression with IL-6 as the outcome variable and BRS-V, age, ACB score, CD4+, sex, Charlson score, and diagnoses of anxiety and depression as the predictors; the final model retained BRS-V (p=0.012) and age (p=0.028)." (PMID 39464041, 2025). "Additionally, vitamin D modulates inflammatory markers such as IL-6 and TNF-α, both central to the systemic inflammation observed in depression." (PMID 40563330, 2025). "Analyzing the immunologic changes that accompany depressive disorder, one meta-analysis of 24 studies on clinical patients reports significantly higher concentrations of the pro-inflammatory cytokines TNF-α and IL-6 in depressed patients compared with control ones." (PMID 40333139, 2025). "The emergence of depressive disorders is predicted by inflammatory indicators such as CRP and IL-6." (PMID 40787495, 2025). "Canonical pro-inflammatory cytokines, such as CRP, IL-1β, IL-6, and TNF-α, influence the central nervous system (CNS) function and contribute to changes in mood, social behavior, emotion regulation, and the onset and prognosis of depressive disorders." (PMID 41333345, 2025). "Based on experimental data, therapy focused on IL-6/STAT3 signaling should be a suitable target for anti-cancer therapy because it can also influence other aspects of malignant disease, such as wasting and depression." (PMID 38715108, 2024). "In recent years, a series of studies have noted that biological indicators in peripheral blood samples, mainly IL-1, IL-6, TNF-α, IFN-α, C-reactive protein, neurotrophic factor and KYN pathway metabolites, can be analysed as criteria for the diagnosis of depression." (PMID 39654767, 2024). "Furthermore, mangiferin downregulates the contents of IL-18, IL-1β, IL-6, and TNF-α in the hippocampus of the CUMS-induced depression mouse model by inhibiting the NLRP3/ASC/caspase-1 pathway." (PMID 38915473, 2024). "The increase of pro-inflammatory cytokines (interleukin (IL)-1β, IL-6, IL-18, and TNF-α) in individuals with depression may elicit neuroinflammatory processes and peripheral inflammation, mechanisms that, in turn, can contribute to gut microbiota dysbiosis." (PMID 38474387, 2024). "Another recent study explored the regulatory role of IL-6 in depression-like symptoms using two rat depression models: chronic unpredictable mild stress (CUMS) and lipopolysaccharide (LPS) administration-induced depression." (PMID 39273641, 2024). "In clinical studies, elevated levels of interleukin-6 (IL-6), interleukin-1β (IL-1β), and tumor necrosis factor-alpha (TNF-α), which belong to pro-inflammatory cytokines, have been observed in patients suffering from depression." (PMID 38892598, 2024).
depression (continued). "This was replicated in a smaller study (n = 92) which also identified elevations in serum IL-6 in those with depression in AD compared to AD without depression and controls." (PMID 39526037, 2024). "Withdrawing regular physical activity increases negative mood in people who do not have depression, which appears to be related to changes in an inflammatory marker, IL-6." (PMID 38961071, 2024). "From the increased levels of proinflammatory cytokines, such as interleukin-6 (IL-6) and tumor necrosis factor-alpha (TNF-α), measured in individuals diagnosed with depression, to the PET scan visualization of neuroinflammation in individuals experiencing depressive episodes." (PMID 38645426, 2024). "In addition, XYS reduced the levels of IL-1β, IL-6, and TNF-α and increased the level of IL-10 in the sera of the mice with depression-like behaviors." (PMID 38378622, 2024). "Moreover, IL-6 is the most persistently elevated cytokine in the blood of MDD patients; so, it may serve as a predictive biomarker and a potential target for the treatment of depression in humans." (PMID 39057075, 2024). "Moreover, the cytokines IL-6, TNF-α, and IL-8 have been suggested as molecules involved in depression, specifically in chronic fatigue and sleep disorders." (PMID 39453274, 2024). "While current evidence strongly suggests a role of IL-6 in depression, research to date has largely focused on circulating levels of IL-6 and other immune proteins rather than their activity, bioavailability, or specific signalling pathways." (PMID 38442505, 2024). "Another previous study in patients with major depressive disorder demonstrated higher serum levels of interleukin-6 in non-responders to antidepressant therapy compared to those in responders." (PMID 38646220, 2024). "Several depression-related cytokines including CCL2, IL-6, and IL-10 were significantly increased." (PMID 39409106, 2024). "Compared to patients without signs of depression, increased serum levels of the inflammatory marker Interleukin-6 were found in patients suffering from depressive symptoms." (PMID 39070588, 2024). "In the course of PD, IL-6 has been found to correlate with the severity of non-motor symptoms in the form of depression, as well as the rate of death." (PMID 38392998, 2024). "In addition, longitudinal analyses revealed that depression is a significant predictor of IL-6 and, conversely, inflammatory markers (CRP or IL-6) predict future depression." (PMID 38474387, 2024). "Elevated serum levels of other circulating cytokines, such as interleukin (IL)-6 and tumour necrosis factor (TNF-α) (depending on the depression subtype), have also been detected during major depression, showing a dose-response relationship with the severity of depression." (PMID 38541828, 2024). "For example, higher interleukin-6 levels in blood precede depression and anti-inflammatory treatments such as non-steroidal anti-inflammatory drugs (NSAIDs) show antidepressant effects." (PMID 38320993, 2024). "Similar numbers of participants had decreases in their FCP, serum CRP, and serum IL-6 in both groups, suggesting that changes in depression scores did not impact measures of IBD activity." (PMID 38839073, 2024). "Indeed, individuals with depression tend to have greater baseline levels of circulating pro-inflammatory mediators, especially TNF-α and Interleukin-6 (IL-6), compared to healthy individuals." (PMID 38928361, 2024). "Three meta-analyses studies have verified that people with a major depressive disorder show elevated serum/plasma IL-6 levels compared to people without depression." (PMID 38560580, 2024).
depression (continued). "By lowering levels of IL-6 and nitric oxide (NO) and caspase-3 and caspase-9 mRNA expression in the hippocampus, epigallocatechin gallate (EGCG) had an antidepressant effect in a rat model of chronic unexpected mild stress (CUMS)-induced depression." (PMID 39459643, 2024). "Another link between depression, cognitive disorders, and CHF seems to be related to alterations of neurohormone levels such as cortisol or to the presence of pro-inflammatory cytokines (IL-6, TNF-α, C-reactive protein)." (PMID 39597044, 2024). "Instead, the associations found in observational studies could be explained by IL-6 and other cytokines acting on both CRP and depression." (PMID 38699297, 2024). "Cytokines like IL-6 and TNF-α are involved in inflammation and immune responses, and their levels are frequently elevated in depressed patients, further supporting the link between inflammation and depression." (PMID 39329797, 2024). "In SLE patients with depression, the abundance of the genus Subdoligranulum was decreased compared to the healthy controls, and it showed a negative correlation with IL-2 and IL-6 at the genus level." (PMID 39457690, 2024). "The amygdala exhibited no changes in glial density with IL-6 KO, which was expected due to the absence of differences in depression-like or anxiety-like behavior." (PMID 38600510, 2024). "In the first study of 31 people with AD and depression, 24 with AD and no depression, and 37 age-matched controls, peripheral IL6 and TNF were elevated in those with AD and depression compared to both those with AD and no depression and controls." (PMID 38175420, 2024). "Subjects with unipolar depression have a significant and positive relationship of CRP serum levels with the “concentration difficulties” item (Rho = 0.262), and IL-6 also with the items “concentration difficulties” (Rho = 0.278) and “lassitude” (Rho = 0.345) on the MADRS Depression Rating Scale." (PMID 38785543, 2024). "Interestingly, these inflammatory mediators are different from the ones previously reported in depression (TNF-α, IL-1β and IL-6)." (PMID 38473935, 2024). "Therefore, in addition to behavioral tests, to investigate the potential correlation between PPT and depression, we also examined the levels of BDNF, NO, IL-6, and 5-HT." (PMID 39062817, 2024). "In a model of LPS-induced depression, fluoxetine (20 mg/kg, i.g.)inhibited glial activation, decreasing levels of pro-inflammatory cytokines such as TNF-α, IL-1β, and IL-6, and increasing levels of the anti-inflammatory cytokine IL-10 in the hippocampus of male C57BL/6J mice." (PMID 38474387, 2024). "Inflammation, marked by elevated pro-inflammatory cytokines like IL-6, TNF-α, and C-reactive protein, is a shared mechanism between depression and dementia, contributing to neurodegeneration, hippocampal damage, and disrupted neuroplasticity, leading to cognitive impairments." (PMID 39429291, 2024). "In the future, we should enroll depressive patients without ENS for a direct comparison of serum IL-6 levels to clarify its role in ENS or just another aspect of a biomarker for depression." (PMID 37324195, 2023). "Consistently, the present study showed that MSD increased the expression levels of the proinflammatory factors IL-1β, IL-6, and TNF-α in the hippocampus, which may have contributed to the depression and cognitive dysfunction in the elderly offspring mice." (PMID 37168717, 2023). "Cancer patients showed increased levels of proinflammatory cytokines (IFN-γ, TNF-α, and IL-6) and oxidative stress markers (MDA and CC levels), which were further significantly enhanced in cancer patients with depression compared to normal healthy (NH) individuals." (PMID 37153524, 2023). "In particular, according to three meta-analyses, subjects with MDD have higher serum/plasma IL-6 levels than those without depression." (PMID 37371695, 2023).